TMBIM4 (transmembrane BAX inhibitor motif containing 4)
Description:
Anti-apoptotic protein which can inhibit apoptosis induced by intrinsic and extrinsic apoptotic stimuli. Can modulate both capacitative Ca2+ entry and inositol 1,4,5-trisphosphate (IP3)-mediated Ca2+ release.
Synonyms: GAAP; LFG4; CGI-119; S1R; ZPRO
Tractability: Antibody: UniProt predicts a signal peptide or a membrane-spanning region.
Gene: Protein-coding gene on chromosome 12 (66,135,846 to 66,170,027, reverse strand). Ensembl gene ENSG00000155957.
Subcellular location: Golgi apparatus membrane
Subcellular location (Human Protein Atlas): Golgi apparatus
Gene Ontology:
Molecular function: protein binding; calcium channel activity
Biological process: negative regulation of apoptotic process; regulation of calcium-mediated signaling; endoplasmic reticulum unfolded protein response; calcium ion transmembrane transport; locomotory behavior; negative regulation of neuron apoptotic process
Cellular component: endoplasmic reticulum membrane; Golgi apparatus; Golgi stack; Golgi membrane
Genetic constraint (gnomAD): Loss-of-function variants: 9 observed, 8.34 expected, observed/expected ratio (o/e) 1.08, 90% interval 0.65 to 1.77. That is too few expected variants to judge how well the gene tolerates losing a copy. Missense variants: 140 observed, 134 expected, observed/expected ratio (o/e) 1.04, 90% interval 0.91 to 1.2. Synonymous variants: 65 observed, 58.13 expected, observed/expected ratio (o/e) 1.12, 90% interval 0.92 to 1.38.
Homologues: Orthologues: chimpanzee TMBIM4 (98% identical), macaque TMBIM4 (97% identical), guinea pig TMBIM4 (90% identical), dog TMBIM4 (89% identical), rabbit TMBIM4 (89% identical), mouse Tmbim4 (84% identical), rat Tmbim4 (84% identical), pig TMBIM4 (80% identical), zebrafish tmbim4 (65% identical), tropical clawed frog tmbim4 (62% identical), Caenorhabditis elegans tmbi-4 (35% identical), Drosophila melanogaster CG33673 (21% identical). Paralogues in human: GRINA (35% identical), FAIM2 (34% identical), TMBIM1 (30% identical), TMBIM6 (26% identical), GHITM (18% identical).
Diseases named in the same sentence as TMBIM4 in open-access papers:
TMBIM4 is named in the same sentence as 89 diseases in open-access papers, as found by Europe PMC text mining. Sharing a sentence is not in itself a finding about the gene and the disease. The quoted sentences say what the papers report.
breast carcinoma (6 papers, 2014 to 2024). "TMBIM4 was found to promote the migration and invasion of human osteosarcoma U2-OS and breast cancer MCF7 cell lines." (PMID 36829486, 2023). "Transmembrane BAX Inhibitor-1 Motif-containing 4 (TMBIM4) was found to promote the migration and invasion of human osteosarcoma U2-OS and breast cancer MCF7 cell lines." (PMID 36829486, 2023). "The cis-eQTL associations of 7 genes (TAPBPL, H1F0, SERPINB9, HMBOX1, MGST3, TMBIM4, THNSL2) are shared between GBM and cell lines/normal tissues; the association of 4 genes (TAPBPL, H1F0, HMBOX1, THNSL2) are common between GBM and Breast Cancer." (PMID 25133526, 2014).
Obesity (2 papers, 2013 to 2022). Accumulation of substantial excess body fat. "TMBIM4 is located within ±1 Mb of the SNP rs1531343 conferring susceptibility to T2DM, while NCKAP5L, TOMM5, and BAP1 are mapped within ±1 Mb of SNPs conferring susceptibility to obesity." (PMID 24455749, 2013). "The rest of the candidates, C2orf15, DENND1B, MRPL30, POC1B, RP4-655J12.3, TMBIM4, BMP2 K, CSRNP2, NCKAP5L, TOMM5, and BAP1, may be novel genes related to T2DM or obesity." (PMID 24455749, 2013).
cervical cancer (1 paper, 2023). A primary or metastatic malignant neoplasm involving the cervix. "In human osteosarcoma U2-OS and cervical cancer HeLa cell lines, TMBIM4 is considered a novel regulator of focal adhesion dynamics, cell adhesion, and migration by activating store-operated Ca2+ entry, thereby stimulating calpain 2 activity to increase the cleavage of focal adhesion proteins." (PMID 36829486, 2023).
cancer (24 papers, 2014 to 2026). A tumor composed of atypical neoplastic, often pleomorphic cells that invade other tissues. "Members of the TMBIM family such as TMBIM1, TMBIM2, TMBIM4, and TMBIM5 are found to be expressed highly in various cancers and also play an important role in cell adhesion and migration." (PMID 31336725, 2019). "Interestingly, TMBIM1, TMBIM2, TMBIM4, and TMBIM5 were found to decrease in many types of cancer, but TMBIM3 and TMBIM6 were significantly increased in this analysis." (PMID 37057283, 2023).
tumor (10 papers, 2014 to 2025). "The expression of TAPBPL, SERPINB9, RCAN1, TMBIM4, JUNB, IL4R, and LY75 is significantly up-regulated in tumor samples with their high expression associated with a poor outcome; the expression of MGST3 is down-regulated in tumor samples with its low expression associated with poor prognosis." (PMID 25133526, 2014).
infection (7 papers, 2014 to 2023). The state of being infected such as from the introduction of a foreign agent such as serum, vaccine, antigenic substance or organism. "Taken together, we speculate that the decreased expression of TMBIM4 in trophoblasts may be responsible for the occurrence of PE by exacerbating trophoblast pyroptosis under infection or non-infection stimuli." (PMID 36829486, 2023).
TMBIM4 also shares sentences with these, for which no sentence is quoted: neurodegenerative disease (26 papers); Alzheimer disease (16); amyotrophic lateral sclerosis (14); Huntington disease (13); depression (10); COVID-19 (8); neurological disorders (6); Parkinson disease (6); retinal degeneration (5); Stroke (5); neuroblastoma (4); Anxiety (3); cognitive deficits (3); diabetes (3); frontotemporal dementia (3); glaucoma (3); liver cancer (3); renal fibrosis (3); schizophrenia (3); viral infection (3); atrial fibrillation (2); cardiac hypertrophy (2); central nervous system diseases (2); colorectal cancer (2); distal hereditary motor neuropathy (2); heart failure (2); ischemic stroke (2); memory impairment (2); pancreatic adenocarcinoma (2); Sepsis (2).
A further 53 diseases each share a sentence with TMBIM4 in 1 paper.